SPP1 (secreted phosphoprotein 1)
Diseases named in the same sentence as SPP1 in open-access papers (continued):
Sharing a sentence is not in itself a finding about the gene and the disease.
breast cancer (continued). "The percentages of high protein expression of CD24, SDC1, and SPP1 were 28.6, 34.2, and 19.2% in breast cancer tissue, compared with 1.5, 1.5, and 1.1% in pan-cancer tissue, respectively (P=0.00, P=0.00, and P=0.00)." (PMID 35037689, 2022). "Inhibition of JNK signalling or down-regulation of SPP1 or TNC can sensitise mammary tumours to chemotherapy and suppress the progression of metastatic breast cancer." (PMID 35260891, 2022). "In the luminal B subtype, SDC1 and SPP1 expression was significantly correlated with prognosis of breast cancer patients." (PMID 35037689, 2022). "The role of SPP1 has been validated in several types of cancers, including in esophageal cancer, ovarian cancer, lung cancer, gastric cancer, and breast cancer." (PMID 35957801, 2022). "SPP1 was significantly upregulated in various malignancies, such as breast cancer, cholangiocarcinoma, glioblastoma, kidney carcinoma, pancreatic cancer, brain lower grade glioma, etc.." (PMID 36292645, 2022). "Previous studies showed that SPP1 is abnormally highly expressed in lung cancer, gastric cancer, colon cancer, breast cancer and liver cancer." (PMID 36585688, 2022). "The expression of CD24, MMP1, SDC1, and SPP1 was much higher in breast carcinoma tissue than in Para cancerous tissues analyzed by Gene Expression Profiling Interactive Analysis (GEPIA) and ONCOMINE." (PMID 35037689, 2022). "Overexpression ofCD24, MMP1, SDC1, and SPP1 indicated the poor prognosis in breast carcinoma patients analyzed by Kaplan–Meier (KM) Plotter." (PMID 35037689, 2022). "Despite this potential limitation, SPP1 was highly expressed in mesenchymal-like aggressive breast cancers, such as those representing the basal-like subtype, when compared to more epithelial less-aggressive subtypes of the disease." (PMID 34832904, 2021). "This was demonstrated by a study that introduced TNBC-like 4T1 mammary tumor cells into SPP1−/− null mice which resulted in decreased spontaneous lung metastasis." (PMID 34832904, 2021). "Several of the LXRE genes predicted increased regression-free survival in breast cancer subjects, among which Ptgs2, Mfge8, Anxa1, Spp1, S100a9 and Cd14 are biomarkers for MDSC and Treg cells." (PMID 33780491, 2021). "Meanwhile, we found that CEP55, HIST1H2BO, IFI6, KIAA0101, PBK, SPAG5, and SPP1 were significantly upregulated in breast cancer compared to normal samples." (PMID 34055036, 2021). "Studies have indicated that SPP1 is elevated in many malignancies, such as ovarian cancer, cervical cancer, and breast cancer." (PMID 34367279, 2021). "Researchers showed that the blocking antibody targeting CD44 on stromal cells reduced the SPP1-induced breast cancer metastasis." (PMID 34676217, 2021). "Circulating and tumor levels of SPP1 positively correlated with a poor prognosis and shortened survival in breast cancer patients." (PMID 34832904, 2021). "SPP1 as the important extracellular matrix component was found overexpression in many kinds of tumors, including PCa, breast cancer, colorectal cancer, and lung adenocarcinoma." (PMID 34721759, 2021). "For instance, SPP1 knockdown in TNBC-like mammary carcinoma cells inhibited tumor growth in both immunocompetent and immunodeficient mice." (PMID 34832904, 2021). "Similar dynamic change was observed in nectin cell adhesion molecule 4 (NECTIN4) and secreted phosphoprotein 1 (SPP1), which have been identified previously as markers for breast cancer progression or metastasis." (PMID 33004987, 2020). "Here, we further investigate the significance of SPP1 and OPN (C- and N-terminals) in predicting recurrence among tamoxifen- treated patients with ER+ breast cancer." (PMID 31996744, 2020). "Using gene expression data available at TCGA database of patients diagnosed with breast cancer and of matching healthy samples, we found that among the identified 11 hits Spp1 (Osteopontin) shows the highest tumour-specific upregulation." (PMID 31964403, 2020).
breast cancer (continued). "Our previous study showed that the development of breast cancer metastasis requires JNK-induced expression of the ECM proteins SPP1 and TNC18." (PMID 32198421, 2020). "Elevated expression of SPP1 has been observed in multiple cancers, including colon cancer, lung cancer, prostate cancer, breast cancer, ovarian cancer, multiple myeloma, acute myeloid leukaemia, and chronic myeloid leukaemia." (PMID 32300605, 2020). "Upon cholesterol treatment, there is a significant increase in the expression of metabolic target genes of ERRα, including IDH3A, VEGF, PDK4, SOD2, GSTM1, and SPP1, in breast cancer cells." (PMID 32717915, 2020). "They demonstrated that constitutive activation of JNK signaling in a human breast cancer cell line promotes significant upregulation of gene expression of ECM proteins such as SPP1 (osteopontin) and TNC (tenascin C)." (PMID 32283767, 2020). "SPP1 was reported to be overexpressed in numerous tumors, such as lung cancer, colon cancer, breast cancer, and prostate cancer." (PMID 31850052, 2019). "Secreted phosphoprotein-1 (SPP1) has been reported to be involved in the pathogenesis of breast cancer (BRC), but the influence of SPP1 single nucleotide polymorphisms on the BRC susceptibility has been rarely reported." (PMID 31921672, 2019). "In this study, we show that activation of the stress‐induced JNK signaling pathway promotes breast cancer progression to metastasis by upregulating SPP1 and TNC, two ECM proteins that normally reside within stem cell niches." (PMID 30190333, 2018). "We found that, similar to SPP1 deficiency, TNC downregulation led to the sensitization of both mammary tumors and lung metastases to paclitaxel treatment." (PMID 30190333, 2018). "We find that deficiency of either SPP1 or TNC, or inhibition of upstream JNK signaling, impairs experimental mammary tumor progression to metastasis." (PMID 30190333, 2018). "The top upstream regulators in malignant mammary tumours were secreted phosphoprotein (SPP1) and coagulation factor II (F2)." (PMID 30517191, 2018). "Spp1 expression remained high in mammary tumors that acquired a more mesenchymal phenotype compared to normal mammary glands." (PMID 27282619, 2016). "Since the claudin-low mammary tumor cell lines expressed higher levels of Spp1 and little is known about the function of OPN in claudin-low breast cancer, OPN function was evaluated in the claudin-low cell line RJ348." (PMID 27282619, 2016). "DNA microarray analysis comparing wild type mammary tissue to the mammary tumors revealed that Spp1 was the most differentially expressed genes; Spp1 was elevated 77-fold in the mammary tumors compared to normal mammary glands." (PMID 27282619, 2016). "Multiple studies have demonstrated a physical interaction between CD44 and Spp1 in a wide variety of cell types, including breast cancer cells, which alters an array of cellular phenotypes including motility and invasiveness." (PMID 24304664, 2013). "In contrast, high expression of SPP1 in other tumors, such as breast cancer, lung cancer, prostate cancer, hepatocellular carcinoma, colon cancer has been associated with tumor progression and metastases." (PMID 17022822, 2006). "The findings provided valuable insight for the development of personalized treatment strategies for breast cancer and indicate that SPP1 may be a therapeutic target." (PMID 41056019, 2026). "At the cellular level, the high expression of SPP1 in monocytes–macrophages can promote malignant phenotypes such as proliferation and migration of breast cancer cells, and its expression level is regulated by myristic acid in significantly differential plasma metabolites." (PMID 41056019, 2026). "Unlike their angiogenic role observed in other tumour contexts, SPP1+ macrophages in breast cancer appear to drive fibrosis and extracellular matrix remodelling, processes that may further fuel tumour progression." (PMID 40395129, 2025).
breast cancer (continued). "In addition, previous study has established that SPP1 promotes tumor cells proliferation through PI3K/Akt signaling pathway in breast cancer." (PMID 41567210, 2025). "SPP1+ TAMs in breast cancer are emerging as pivotal modulators of the tumour microenvironment." (PMID 40395129, 2025). "Moreover, in a synthetic metastatic niche model of breast cancer, Spp1 emerged as a niche-specific gene signature for neutrophils and was associated with a Th17 response–dependent recruitment and activation." (PMID 40865052, 2025). "Notably, the overexpression of ERα, ERRα, and SPP1 was further corroborated by their presence in human breast cancer tissues, suggesting a conserved mechanism across species." (PMID 39682141, 2024). "This study aimed to understand how GCR might lead to breast cancer by focusing on a hormone-related pathway involving estrogen receptor alpha (ERα) and other related molecules (ERRα and SPP1)." (PMID 39682141, 2024). "Additionally, ERRα expression was elevated, and there was an accumulation of the preneoplasia marker SPP1 in GCRsim-exposed mice, indicating a synergistic effect of both receptors on mammary cancer progression." (PMID 39682141, 2024). "Furthermore, the higher co-expression of Esr1, Esrra and Spp1 mRNA in human breast cancers emphasizes the importance of ERRα in conjunction with ERα in driving SPP1 expression and, potentially, breast cancer progression." (PMID 39682141, 2024). "Additionally, ERRα expression, particularly through its regulatory effects on SPP1, underscores the potential importance of estrogen and inflammatory crosstalk in IR-induced breast cancer." (PMID 39682141, 2024). "Notably, Sparc, Spp1, and Cdh2 were found to be upregulated in the human breast cancer samples included in TCGA database, consistent with the clinical relevance of Mbd2-regulated genes in breast cancer." (PMID 38556549, 2024). "In this ground-based mouse model study, we exposed female ApcMin/+ mice to GCRsim at NASA’s Space Radiation Laboratory (NSRL) and focused on understanding the roles of PER, ERRα, and SPP1 signaling in GCRsim-exposed ApcMin/+ mice to elucidate their contributions to breast cancer development." (PMID 39682141, 2024). "Moreover, in TNBC, SPP1-expressing macrophage communication was exclusive to younger patients, while in ER+ breast cancer, it was exclusive to older patients." (PMID 39483921, 2024). "The association between SPP1 protein expression, BRCA, and TNBC survival prompted us to investigate the prognostic potential and clinical relevance of SPP1 protein expression in our breast cancer cohort study." (PMID 39727934, 2024). "Many studies have described the overexpression of SPP1 in multiple cancers such as breast carcinoma, hepatocellular carcinoma, penile cancer, ovarian carcinoma, and lung adenocarcinoma, as well as the key roles of SPP1 in invasion, metastasis, chemoresistance, and immune suppression." (PMID 39409192, 2024). "In breast cancer, the inhibition of SPP1 and CSF1 could prevent the assembly of an immunosuppressive tumor microenvironment and partially or completely sensitize otherwise refractory quasi-mesenchymal tumors to anti-CTL4 immune checkpoint blockade therapy." (PMID 37097499, 2023). "Upon investigating the mammary tumor tissue from docetaxel-treated mice, we found an increase in protumor immune infiltrates including M2 macrophages, MDSCs, Tregs, γδT cells, and an enriched gene signature comprising Vim, Spp1, S100a6, Ccl2, and Lgals1 genes." (PMID 37699010, 2023). "In our study, SPP1 expressed much higher in breast cancer tissue than in para cancerous tissues." (PMID 35037689, 2022). "Secretory phosphoprotein 1 (SPP1), also known as bone bridge protein (OPN), is an integrin-binding glycophosphoprotein and has been shown to be overexpressed in many cancers such as hepatocellular carcinoma, lung cancer, prostate cancer, and breast cancer." (PMID 36510497, 2022).
breast cancer (continued). "In addition, EMT biomarkers CDH1 and VIM were highly expressed in cancer cells, consistent with previous reports showing that TAM promoted EMT progress of cancers (lung cancer, colorectal cancer, breast cancer and ovarian cancer) by SPP1." (PMID 36148946, 2022). "SPP1 is also widely known to contribute to the migration of breast cancer cells to bone." (PMID 35453667, 2022). "SPP1 expression was correlated with the Luminal B breast cancer tissue." (PMID 35037689, 2022). "In a prospective cohort of breast cancer patients received adjuvant chemotherapy, the SPP1 expression level could predict the efficiency of neoadjuvant chemotherapy in certain patients." (PMID 34721759, 2021). "However, given the impact of SPP1/OPN on breast cancer progression in preclinical studies, the search for effective and safe SPP1/OPN targeted therapies should continue." (PMID 34832904, 2021). "Using metadata analysis of clinical cohorts, reported datasets and TCGA patient data extraction, we identified Spp1 as a particularly promising target, since the high expression of this gene in breast cancer patients is coupled to poor patient survival and metastasis." (PMID 31964403, 2020). "Additionally, JNK signaling promoted stem cell properties, including sphere formation and invasion ability, and treatment of a breast cancer mouse model with paclitaxel-induced SPP1 and TNC expression via JNK signaling." (PMID 32283767, 2020). "It is thus significant that cholesterol binding to ERRα and cholesterol-mediated increase in ERRα-PGC-1α interaction result in increased expression of ERRα itself and its metabolic target genes including IDH3A, VEGF, SOD2, GSTM1, PDK4, SPP1 in breast cancer cells." (PMID 32717915, 2020). "Higher SPP1 gene expression in primary tumours was found to be associated with risk of recurrence in ER+ breast cancer among patients with endocrine treatment, while OPN protein expression does not appear to be predictive of recurrence." (PMID 31996744, 2020). "SPP1 have been demonstrated to induce NF-κB activation in breast cancer cells." (PMID 31481087, 2019). "Moreover, SPP1 has been shown to induce cellular motility in breast cancer cells and to be a member of a gene set that mediates breast cancer metastasis to the bones." (PMID 30190333, 2018). "Importantly, JNK inhibition or disruption of SPP1 or TNC expression sensitizes experimental mammary tumors and metastases to chemotherapy, thus providing insights to consider for future treatment strategies against metastatic breast cancer." (PMID 30190333, 2018). "Notably, inhibition of JNK signaling or repression of SPP1 or TNC expression can sensitize mammary tumors and lung metastases to chemotherapy." (PMID 30190333, 2018). "In addition, SPP1 is involved in the remodeling of the breast cancer microenvironment." (PMID 41056019, 2026). "In the breast cancer dataset GSE213474, many pathways related to cell growth and division were found to involve genes that had shown a significant downregulation with the application of IFN-γ treatment, including integrin cell surface interactions, a significant hallmark of SPP1 action." (PMID 39857756, 2025). "Interestingly, using serial normal and tumor tissue sections, we found that both ERRα and SPP1 concurrently overexpressed in the different breast cancer tissues including invasive lobular carcinoma, fibroadenoma, and invasive ductal carcinoma compared to the normal breast tissues." (PMID 39682141, 2024). "In addition to PER activation, female ApcMin/+ mice exposed to GCRsim have shown increased accumulation of secreted phosphoprotein 1 (SPP1, also known as osteopontin or OPN) in the ductal epithelium, which serves as a preneoplastic marker for breast cancer risk." (PMID 39682141, 2024).
breast cancer (continued). "In breast cancer, SPP1 derived from TAMs has been suggested to be involved in cancer cell growth and progression, and single-cell RNA sequence analysis has indicated that SPP1 is highly expressed in monocyte-derived TAMs as compared with resident macrophages/TAMs." (PMID 37190178, 2023). "Hence, further study is required to determine whether MMP1, CD24, SDC1, and SPP1 could be used as biomarkers or immune therapy targets in breast cancer." (PMID 35037689, 2022). "SPP1 could have an important role as an immune therapy target in breast cancer." (PMID 35037689, 2022). "In our results, high expression of MMP1, CD24, SDC1, and SPP1 correlated to the development of breast cancer, worse OS and immune cell infiltration, indicating that MMP1, CD24, SDC1, and SPP1 might be as the potential prognostic biomarkers and immunotherapy targets for breast tumor." (PMID 35037689, 2022). "Therefore, SPP1 expressed in both the microenvironment and in the tumor may support breast cancer metastasis." (PMID 34832904, 2021). "SPP1 deficiency did not affect mammary tumor growth in this model." (PMID 30190333, 2018). "However, neither SPP1 deficiency nor chemotherapy alone resulted in reduced mammary tumor growth, yet chemotherapy or SPP1 deficiency individually caused a moderate and a significant reduction in lung metastasis, respectively." (PMID 30190333, 2018). "For instance, GPNMB overexpresses in a breast cancer cell line that could aggressively metastasize to bone, and SPP1's expression level (also called Osteopontin) is elevated in a variety of metastatic cancers, including colon cancer, hepatocellular carcinoma, and gastric cancer." (PMID 22078224, 2011). "Mapping SNPs to genes showed that two genes (SPP1 and ADM2) were significantly upregulated in breast cancer." (PMID 41056019, 2026). "It was suggested that the downregulation of miR-944 facilitates the expression of SPP1, which subsequently stimulates the PI3K/AKT/mTOR pathway in in vitro experiments with breast cancer cells." (PMID 40142329, 2025). "In vivo experiments confirmed that miR-944 plays the anticancer role, suppressing SPP1 and the PI3K/AKT/mTOR pathway in breast cancer." (PMID 40142329, 2025). "In the breast cancer study GSE213474, MCF7 cells treated with IFN-γ stimulation showed SPP1 to be significantly downregulated in samples (log2FC = −2.067, p-value = 0.038), when the treatment was applied for a longer duration (48 h v/s 24 h)." (PMID 39857756, 2025). "For instance, overexpression of osteopontin (SPP1) has been shown to upregulate key epithelial–mesenchymal transition (EMT) transcription factors, thereby promoting aggressive phenotypes in breast cancer." (PMID 41288989, 2025). "Worthy, the signature demonstrated to predict poor outcomes in breast cancer patients exhibiting high transcriptional levels of ITGA11, THBS1, FN1, EMP1, ITGA2, FYN, SPP1, and EMP2." (PMID 38937754, 2024). "In concurrence to activation of ERα, ERRα, and SPP1 signaling axis in GCRsim-induced tumors, using TMA, we noted elevated expression of ERRα and SPP1 in human breast cancer tissues, including invasive lobular carcinoma and invasive ductal carcinoma." (PMID 39682141, 2024). "In spontaneously metastatic models of breast cancer, host-derived osteopontin (OPN, Spp-1), a matricellular protein particularly produced by the monocytic subset of myeloid-derived suppressor cells (MDSCs), renders the metastatic site more immunosuppressive." (PMID 39402303, 2024). "The scRNA Seq dataset analysis also confirmed the positive correlation between Wdr5 and PD-1, PD-L1, and Spp1, as well as the positive correlation between Wdr5 and both TGFβ and IL6 in both human colon cancer and human breast cancer." (PMID 39201460, 2024). "Additional scRNA‐seq data from human breast cancer identifies a monocyte‐derived macrophage population expressing TREM2, SPP1, C1QA, and APOE." (PMID 38426622, 2024).